IL2 (interleukin 2)
Diseases named in the same sentence as IL2 in open-access papers (continued):
Sharing a sentence is not in itself a finding about the gene and the disease.
food allergy (18 papers, 2011 to 2025). Gastrointestinal disturbances, skin eruptions, or shock due to allergic reactions to allergens in food. "Therapeutic interventions such as oral immunotherapy and administration of low-dose interleukin-2 (IL-2) have been shown to enhance Treg functionality, thereby representing promising strategies for the management of food allergies such as peanut allergy." (PMID 40142710, 2025). "Compared with the food allergy model group, the expression of the Th1 cytokines IL-2 and IFN-γ in the middle-dose ZW3 and high-dose ZW3 groups was notably enhanced (p < 0.05)." (PMID 39796306, 2024). "IL-2-5344 has also shown efficacy in suppressing experimental food allergy in mice, and IL-2-5111.2 favored the expansion of Tregs in humanized mice and halted progression of T1D, EAE, and GvHD." (PMID 36399073, 2023). "Recently, it has been reported that low-dose IL-2 or a combination of IL-2/anti-IL-2 restored Treg numbers and function in respiratory and food allergies, thereby improving allergic markers and symptoms." (PMID 35720406, 2022). "Using Tregs isolated from PBMC’s from patients with severe food allergy, Jennifer Jenks from Kari Nadeau’s lab was able to demonstrate a similar defect in inhibition of the Treg IL-2R response to activation by low dose IL-2." (PMID 36569931, 2022). "In addition, a mechanism associated with IL-2 has been identified, through the supplementation of IL-2 to mice with peanut allergy, where the supplemented mice presented increased function and number of Treg cells, therefore prevention of food allergy for a period of 7 months." (PMID 34993254, 2021). "It has been reported that low-dose IL-2 can induce the expansion of Tregs, which has great potential in the treatment of food allergy." (PMID 34203383, 2021). "Low doses of IL-2–induced Treg expansion provides protection against clinical manifestation of food allergy by Treg-dependent modification of Th1/Th2 balance." (PMID 33571165, 2021). "Our results indicate that naive T cells from children with food allergy, although they appear immunocompetent in relation to IL-2 production, exhibit an intrinsic molecular defect during the early state of priming, and depressed capacity for proliferation." (PMID 30120223, 2018). "Additionally, low dose IL-2 has been used to treat experimental food allergy." (PMID 36569931, 2022). "In cord blood, infants who developed food allergies showed a higher ratio of monocyte/CD4+ T cells, which would secrete higher amounts of inflammatory cytokines, such as IL-1β, IL-6, and TNF-α that further suppressed IL-2 expression by CD4+ T cells." (PMID 38263182, 2024). "Interestingly, regulatory DCs stimulated with IL-2 and antigen produce exosomes carrying IL-2 and p-MHCII complexes which promote Tregs and suppress allergic inflammation in a murine model of food allergy." (PMID 35062793, 2022). "Here, we tested the impact of an IL-2 agonist in a novel model for food allergy to hen ́s egg in mice sensitized without artificial adjuvants." (PMID 33362780, 2020). "Although increased production of IgE and Th2 cytokines (IL-4, IL-5 and IL-13) are considered common markers of food allergy, absence of IgE or increased levels of Th1 cytokines (IL-2, IFN-γ and TNF-α) have also been observed in several instances of food allergy, mainly in response to cow's milk." (PMID 21211037, 2011).
latent infection (18 papers, 2009 to 2025). "However, few studies evaluated the performance of IL-2 and IP-10 in subjects with latent infection or at high risk of TB exposure, especially in a TB-endemic and BCG-vaccinated area." (PMID 28033330, 2016). "Their activation attenuated the immune response throughout latent infection probably by decreasing the availability of the potent proinflammatory IL-2." (PMID 39853582, 2025). "Cytokine expression profiles (IL-2, IL-4, IL-6, and IL-10) were analyzed in the latent infection model using flow cytometry." (PMID 40388758, 2025). "First, we determined the levels of total, productive, and latent infection in IL-2-stimulated cells." (PMID 35499323, 2022). "Using the CCL19 model of HIV latency, we found that in up to 50% of donors, CCL19 enhanced latent infection of resting CD4+ T-cells by CXCR4-tropic HIV in the presence of low dose IL-2." (PMID 27383184, 2016). "When assessing cytokine profiles, PPD specific CD4 T cells secreting both IFN-γ and IL-2 predominated in treated TB, latent infection and BCG-vaccination, whilst in active TB the cytokine profile was shifted towards cells secreting IFN-γ only (p<0.0001)." (PMID 21423578, 2011). "Collectively, the PPD-stimulated IL-2/IFN-γ ratio after long-term incubation may be an alternative diagnostic biomarker in distinguishing between active TB patients and subjects with latent infection." (PMID 28033330, 2016). "In addition, the Ag85b/ESAT6/CFP10-specific IFN-γ cell immune response and the ESAT6-specific IL-2 cell immune response induced by AEC/BC02 in the Mtb latent infection mice were both higher than those in normal mice, while Ag85b/CFP10-specific IL-2 cell immunity was lower than that in normal mice." (PMID 35632581, 2022). "The optimum sensitivity of 77.2% and specificity of 87.2% of the IL-2/IFN-γ ratio in detecting ATB from LTBI (cut-off value of 1.133) suggested that this ratio may not function as a stand-alone diagnostic indicator of LTBI, but one of the valid methods to distinguish active TB from latent infection." (PMID 23272100, 2012). "A latent infection was established using DHIV-GFP (day 7), and at day 14, cells were labeled with CPe670; cells were then treated with either IL-2 alone or IL-2+IL-7." (PMID 21998586, 2011). "The results of the linear regression analysis showed that the correlation between IL-2 and TNF-α in the LTBI population was as good as R2 = 0.9655, suggesting a significant positive correlation between IL-2 and TNF-α in the process of immune response to latent infection." (PMID 37112768, 2023).
lung fibrosis (18 papers, 2010 to 2025). "In the mouse model of bleomycin-induced pulmonary fibrosis, CD4 + CD25highFoxP3+ cells in the lung were increased after IL-2 complex treatment associated with aggravated lung fibrosis." (PMID 36979470, 2023). "Another study induced the proliferation of Treg via IL-2 complex injection in mice, which worsened lung fibrosis after BLM injury." (PMID 39737178, 2024). "Researchers found an increase of Treg in AE-IPF mice, and depletion of Treg worsened infection-induced fibrosis, while IL-2 complex-induced Treg expansion with established lung fibrosis inhibited fibrosis exacerbation induced by pneumococcal infection." (PMID 39737178, 2024). "Apart from that, interleukin 18 can also promote the secretion of cytokines, such as interferon-γ and interleukin 2 by Th1 cells, which then enhances type 1 hypersensitive responses to delay the further progression of pulmonary fibrosis." (PMID 30719057, 2019). "Data presented demonstrate that pulmonary CFPs from silica-induced pulmonary fibrosis exhibit an inhibitory role toward the Th1 phenotype based on decreased production of IL-2 and IFN-γ by CD4+ and CD8+ T cells." (PMID 28700752, 2017). "Secondly, we want to investigate the regulatory role of CD4+CD25+Foxp3+ Treg cells in silica-induced lung fibrosis by studying the mRNA expression of typical Th1 (IL-2, IFN-γ) and Th2 (IL-4) cytokines." (PMID 21072213, 2010). "A growing number of studies have shown that Th1 cells exert resistance to lung fibrosis by inducing an inflammatory response in the lung through the release of pro-inflammatory cytokines IL-2, interferon-gamma (IFN-γ), tumor necrosis factor(TNF), IL-12, and IL-18 production." (PMID 40433386, 2025). "EMT, TGF-β, hyperproliferation of myofibroblasts and high levels of pro-inflammatory IL-2, IL-7, and IFN-γ, are extensively involved in pulmonary fibrosis during SARS-CoV-2 infection." (PMID 39469708, 2024). "GSEA showed that DEGs in the CIP associated myeloid cell subclusters were enriched in inflammation pathway such as IFN, IL2, IL6, TNF signaling, and lung fibrosis." (PMID 37653115, 2023). "Increased levels of IL1ꞵ, IL2, IL6, IL8, IL10, and IL12 have been reported in the bronchoalveolar lavage fluid and/or serum of patients with pulmonary fibrosis compared to healthy subjects." (PMID 34960806, 2021). "Results showed that LPSF/GQ-16 not only influenced the PBMCs’ production of IL-2, IL-4, IL-6, IL-17A, TNF, and IFN-γ, but also reduced skin thickening, downregulated biomarkers of skin and lung fibrosis, as well as decreased the activation of immune cells in the experimental model." (PMID 37833885, 2023).
pyrexia (18 papers, 1983 to 2026). "Grade 3 events were mainly those associated with IL2, most commonly rigors (3 patients) and pyrexia (2 patients)." (PMID 19640287, 2009). "The most common grade 3 events were rigors (patients 0004–4101, 0004–4102, 0004–4104) and pyrexia (patients 0004–4101, 0004–4102), which are known to be associated with IL2-based therapy and were attributed to the study drug." (PMID 19640287, 2009). "Fever is known to be the most frequent symptom of cytokine storms, mainly associated with the over-activation of neutrophils, monocytes, macrophages, T cells and massive release of cytokines (such as IL-6, IL-2, IFN-γ, TNF-α)." (PMID 39127636, 2024). "Fever is clinically common adverse reaction caused by IL-2, some patients need anti-fever drugs." (PMID 29980186, 2018). "AEs that tended to be more common in the IL-2 + IFNα group in all grades were pyrexia (72% vs. 33%, p = 0.025) and malaise (50% vs. 27%, p = 0.172)." (PMID 37345082, 2023). "Fever was the most common adverse effect in sequential administration period of interleukin-2 and GM-CSF." (PMID 34722242, 2021). "Side effects noted shortly after administration of the partially-purified IL-2 preparations included transient pyrexia, hypoglycaemia, increased cortisol levels, lymphocytopenia and signs of mild intravascular coagulation." (PMID 6600395, 1983). "With respect to the side effects of IFN-α and IL-2, it has been reported that pyrexia, fatigue, headache, and myalgia were generally observed, while severe complications such as hematopoietic inhibition or hepatic decompensation were occasionally seen in long-term use of them." (PMID 22722448, 2012). "In addition, all patients experienced grade 1 or 2 IL2-related adverse events including nausea, rigors or pyrexia." (PMID 19640287, 2009). "Proinflammatory mediators, IL-2, and PGE2, are among the important mediators of LPS-induced pyrexia." (PMID 23970953, 2013). "In this study, as short-term administration and limited dose of IFN-α and IL-2 were employed, we observed no more than slight pyrexia, fatigue, headache, myalgia in some patients." (PMID 22722448, 2012). "Notably, the percentages of IL-2+ and IFN-γ+ CD4+ T cells were significantly higher in the fever-positive donors after the first dose, rather than after the second dose, in both groups." (PMID 37118516, 2023).
T cell lymphoma (18 papers, 1985 to 2026). "We then cultured PBMCs from another patient with EBV-associated T cell lymphoma (Patient 3) and from a healthy donor with IL-2-supplemented media." (PMID 27732937, 2016). "Murine T-cell lymphoma BW5147 cells are capable of producing IL-2, but only a trace amount of IFN-γ, in response to phorbol 12-myristate 13-acetate (PMA) and A23187, which mimic T-cell receptor stimulation." (PMID 40430387, 2025). "Cytokines like IL-2 and IL-7 are well-established mediators of T-cell lymphoma metabolic reprogramming." (PMID 37746258, 2023). "An example is the immunotoxin denileukin diftitox, that incorporates the interleukin-2 (IL-2) fused to the diphtheria exotoxin domain to target T cell lymphoma cells that overexpress the IL-2 receptor." (PMID 35120582, 2022). "Our data showed that the K607E mutation in BCOR—which results in the protein being unable to bind to BCL6— significantly enhanced cell proliferation, AKT phosphorylation, and IL-2 production in T cell lymphoma lines." (PMID 33468080, 2021). "For example, diphtheria toxin, which ADP-ribosylates eEF2, conjugated to interleukin-2 (ONTAK) has been approved by the FDA for the treatment of T-cell lymphomas." (PMID 34508355, 2021). "Primary extra-nodal NK/T cell lymphoma tissue was dissociated into single cells and expanded in the presence of IL-2." (PMID 31126350, 2019). "Cells tested included the IL-3-dependent murine pro-B cell line, Baf3, the IL-2-dependent human T cell line, Kit225, and the human T cell lymphoma cell line, HH." (PMID 27444277, 2016). "Growth factor independent-1 (Gfi1) is a transcriptional repressor originally identified as a common proviral insertion site of the murine Moloney leukemia virus (MMLV) that conferred IL-2 independent growth to IL-2 dependent T-cell lymphomas." (PMID 24068942, 2013). "The IL2 pathway is an immune signaling pathway that is commonly down regulated in tumors like T-cell lymphoma." (PMID 22536907, 2012). "In response to a phorbol 12-myristate 13-acetate (PMA) and ionomycin (IM) stimulation, kujigamberol suppressed interferon-γ (IFN-γ) and interleukin-2 (IL-2) mRNA expression in murine T-cell lymphoma BW5147 cells stably transfected with the T-box transcription factor eomesodermin." (PMID 40430387, 2025). "GRB2 knockdown and re-expression of selected monomeric and dimeric mutants in a T cell lymphoma cell line led to notable defects in clustering of the adaptor protein LAT and IL-2 release in response to TCR stimulation." (PMID 36864087, 2023). "Parental BW5147 cells are murine T-cell lymphoma cells that produce high levels of IL-2 and no or trace levels of IL-4 and IFN-γ, respectively." (PMID 40430387, 2025).
cutaneous melanoma (17 papers, 2003 to 2026). A primary melanoma arising from atypical melanocytes in the skin. "And finally, a retrospective study of patients with cutaneous melanoma metastases demonstrated the use of intralesional IL-2 with topical imiquimod and retinoid cream as a promising therapeutic regimen." (PMID 41234721, 2025). "Cytokines, including the interleukin IL-2 and IL-21 ligands identified in cutaneous melanoma, regulate innate and adaptive immunity." (PMID 36676129, 2023). "The impact of IL‐2 expression on the patient survival with lung adenocarcinoma and skin cutaneous melanoma in TCGA using the Kaplan–Meier survival analysis was investigated." (PMID 36684086, 2023). "Various drugs, alone or in combination, including vinblastine, bleomycin, lomustine, vincristine and recently recombinant interferon-alpha and interleukin-2, have been used with varying results as palliative treatment of cutaneous melanoma." (PMID 16613599, 2006). "In patients with stage IV or locally advanced stage III cutaneous melanoma, the combined use of interleukin-2 (IL-2) therapy and the gp100 peptide vaccine resulted in an improved response rate and progression-free survival rate compared to the use of IL-2 therapy alone." (PMID 31533363, 2019). "However, IL-2 administered intravenously was observed in a subgroup of 28 patients with subcutaneous and cutaneous melanoma metastases respectable 53% responder." (PMID 14583759, 2003). "Therefore, development of macroscopic cutaneous melanomas could impair the secretion of IL-2 and IFN-γ by T cells upon antigen-unspecific stimulation, whereas cells from transgenic tumor free mice were able to mount strong cytokine responses." (PMID 24213320, 2012). "Treatment is based on drugs developed for advanced cutaneous melanoma and includes cisplatin, vinblastine, dacarbazine, INF, and interleukin-2, although given the clinical, biologic, and molecular differences, mucosal and cutaneous melanomas may be distinct disease entities." (PMID 19671138, 2009). "In particular, in a population of 30 patients with primary cutaneous melanoma and studied with 99mTc-IL2, CD25 was detected in TILs in 15 tumours of which 11 demonstrated 99mTc-IL2 uptake by imaging." (PMID 31091813, 2019).
dermatitis (17 papers, 2014 to 2025). An inflammatory process affecting the skin. "The researchers observed an increase in the severity of dermatitis with an increase in IL-2 and IL-17 expression levels and a decrease in the severity of dermatitis with a decrease in the expression of IL-4 and IL-10 expression levels." (PMID 35431950, 2022). "Compared with inflamed dermatitis mice, the contents of tnf-α, ifn-γ, il-2, and il-17a were significantly lower in mice that received isovitexin." (PMID 34456714, 2021). "Malt1-KO mice that develop skin inflammation were found to have increased serum levels of the pro-inflammatory cytokines IL-2, IL-4, IL-6, IL-17, IFN-γ, and TNF." (PMID 31632405, 2019). "Additionally, some drugs (griseofulvin, ethionamide, buspirone, haloperidol, chlorpromazine, IL-2, interferon-α, methyldopa, psoralens) and nutritional deficiencies (pyridoxine, zinc, niacin and riboflavin) may induce an SD-like dermatitis, although the mechanism remains unknown." (PMID 27148560, 2015). "The upregulation of MMP-9 and IL-2 after UVB induction may be closely related to skin inflammation and immune abnormalities." (PMID 40232010, 2025). "Since the ratio of activated T cells to Tregs in the skin was significantly higher in KitW-sh/W-sh mice reconstituted with Il2-/- MCs than in those reconstituted with WT MCs, it was concluded that MCs inhibit dermatitis by maintaining Tregs via IL-2 production." (PMID 35634300, 2022). "We identified a critical role of proinflammatory cytokines such as TNF-α, IFN-γ, IL-2 and IL-17A in skin inflammation in this model and revealed that these cytokines may be regulated by SHP2 in vitro." (PMID 34456714, 2021). "Though IL-2 and IL-7 are largely homeostatic for ILC2 responses, there is one report that demonstrated that IL-2 treatment of RAG1 deficient mice (lack B and T cells, but have ILC2s) led to increased ILC2 proliferation, activation, and dermatitis." (PMID 28959799, 2017). "Interestingly treatment of Rag1−/− mice with IL-2 and anti-IL-2 complex (JES6-1) for 2–3 weeks induced spontaneous skin inflammation around ears, eyes, mouth and tail." (PMID 25427661, 2014). "All mice with oxazolone-induced dermatitis had a dramatic increase in IL-1β, IL-4, IL-6, IL-10, TNF-α, IFN-γ, IL-16, IL-17C, IL-17E, IL-17F, IL-21, IL-22, and MIP-3a, whereas the concentrations of IL-12p70, IL-2, IL-17A, and IL-23 were lower in dermatitis mice." (PMID 37889696, 2023).